FN1 (fibronectin 1)
Diseases named in the same sentence as FN1 in open-access papers (continued):
Sharing a sentence is not in itself a finding about the gene and the disease.
renal hypertension (1 paper, 2016). Hypertension caused by the kidney's hormonal response to narrowing or occlusion of the renal arteries. "Seven of them (Agtr1a, Fn1, Gja1, Lama2, Mmp2, Mmp9, Nos3) are known as being associated with renal hypertension." (PMID 28105926, 2016). "The changes in expression of DEGs associated with renal hypertension (Agtr1a, Fn1, Gja1, Lama2, Mmp2, Mmp9, Nos3) may also be suggested to have a significant impact on disease development in ISIAH rats." (PMID 28105926, 2016).
Renal insufficiency (1 paper, 2022). A reduction in the level of performance of the kidneys in areas of function comprising the concentration of urine, removal of wastes, the maintenance of electrolyte balance, homeostasis of blood pressure, and calcium metabolism. "Relevant literature have shown that IL6, AKT1, VEGFA, FN1, TIMP1, ALB and TNF are associated with renal insufficiency." (PMID 36209090, 2022).
retinal detachment (1 paper, 2020). An eye emergency condition which may lead to blindness if left untreated. "FN1 is a major component of the extracellular matrix of PVR membranes found within the vitreous and along retinal surfaces of PVR patients, whose contraction results in concurrent retinal detachments." (PMID 33347461, 2020).
retinoblastoma (1 paper, 2011). A malignant tumor that originates in the nuclear layer of the retina. "To further test the correlation between histone H4 acetylation and FN1 splicing, we analyzed H4 acetylation in a retinoblastoma derived cell line Y79 that almost exclusively included the alternative exon." (PMID 21311748, 2011).
salivary gland carcinoma (1 paper, 2018). A carcinoma that arises from the major or minor salivary glands. "miR-200 family target protein, fibronectin 1, FN1 which was seen to be 1.6 fold overexpressed in OKF6/TERT1-Smoke cells is reported to be overexpressed in salivary gland carcinoma and in OSCC patients with lymph node metastasis." (PMID 29728663, 2018).
salivary gland neoplasm (1 paper, 2022). Tumors of the SALIVARY GLANDS. "The resulting candidate genes as possible therapeutic targets were FN1, SPP1, EGF, and ERBB2, and all those genes had been tested as a target in other neoplasm kinds but not salivary gland neoplasm." (PMID 36146635, 2022).
small bowel adenocarcinoma (1 paper, 2022). "Four target genes (APOA4, APOB, COL1A2, FN1) may be involved in the pathogenesis of small bowel adenocarcinoma." (PMID 36171259, 2022).
tendinopathy (1 paper, 2023). "Also, upregulation of genes encoding proteoglycans (BGN) glycoproteins (TNC, FN1, SPARC), integrins (ITGB1), and growth factors has been reported in tendinopathy patients." (PMID 38001919, 2023).
tongue cancer (1 paper, 2020). A malignant neoplasm affecting the tongue. "The present study demonstrated that SPP1 was significantly upregulated in tongue cancer, suggesting that FN1 and SPP1 play important roles in the development of tongue cancer." (PMID 32236620, 2020). "In the present study, FN1 was found to be highly expressed in tongue cancer tissues." (PMID 32236620, 2020).
trichinellosis (1 paper, 2025). "This study suggests that S. officinalis possesses strong antifibrotic and anti-inflammatory properties, by downregulating FN1, TNF-α, and TGF-β while maintaining IL-10 expression, making it a valuable adjunct therapy for trichinellosis." (PMID 41026274, 2025).
ventricular dilatation (1 paper, 2019). "Mice lacking FN1 extra domain A also exhibited reduced fibrosis and ventricular dilatation following acute MI." (PMID 31920673, 2019).
vitiligo (1 paper, 2024). Generalized well circumscribed patches of leukoderma that are generally distributed over symmetric body locations and is due to autoimmune destruction of melanocytes. "Thus, it could be hypothesized that FN1 is an essential molecular marker for ZNF90+ fibroblasts, which facilitates repigmentation when transplanting cultured epithelial sheets onto patients with vitiligo." (PMID 38200141, 2024).
Zinc deficiency (1 paper, 2025). A deficiency of the essential metal Zinc; an essential cofactor for many enzymes. "Furthermore, our quantitative analysis confirmed a substantial upregulation of α-SMA, Col III, and FN1 as fibrosis markers in the group with zinc deficiency." (PMID 39028478, 2025). "In this study, we conducted a comprehensive assessment of the expression patterns of key EMT markers (N-cadherin, E-cadherin, Vimentin, SNAIL) and fibrosis-related markers (α-SMA, FN1, Col III) in a rat model with zinc deficiency using qPCR, WB analysis, and IHC." (PMID 39028478, 2025). "Furthermore, zinc supplementation led to a significant reduction in the expression of fibrosis markers α-SMA, FN1, and Col III, suggesting its potential efficacy in inhibiting EMT progression and renal interstitial fibrosis induced by zinc deficiency." (PMID 39028478, 2025).
tumor (893 papers, 1995 to 2026). "Recent data obtained dissecting ovarian CAF populations by ATAC and scRNA seq analysis revealed that the myCAF cluster containing COL1A1 and FN1 is the most critical for tumor growth and metastasis, associated with short-term survival." (PMID 39985042, 2025). "FN1, a crucial extracellular matrix protein, promotes tumour cell adherence and migration, and its noted association with heightened infiltration of Activated CD8 T cells and MDSCs." (PMID 40475773, 2025). "CF1, SSP1, and FN1 encode extracellular proteins that were highly overexpressed in the tumor samples analyzed, suggesting their potential utility as non-invasive diagnostic biomarkers." (PMID 41369478, 2025). "Ligands participating in these interactions are known immunosuppressive molecules (e.g., Tgfb1, Il1b), pro-angiogenic factors (e.g., Vegfa), or other genes associated with tumor progression (e.g., Fn1, Apoe, Apoc2)." (PMID 40216735, 2025). "Our results showed a favorable association between tumor-infiltrating immune cells and FN1, CXCL8, IL1β, and ITIH4." (PMID 38637796, 2024). "More importantly, many of the downregulated genes (Fn1, Hspb1, Postn, Mia, Fgfr1, Serpine2) have been associated with tumor metastasis." (PMID 39287984, 2024). "Overexpression of fibronectin 1 (FN1) is associated with tumor progression by promoting proliferation, invasion, and metastasis." (PMID 38267588, 2024). "We further demonstrate that THUMPD3 maintains expression of an extra-domain B (EDB) containing pro-tumour isoform of Fibronectin-1 mRNA, encoding FN1, an important ECM protein." (PMID 39656728, 2024). "The expression of COL4A1 (encoding collagen IV chains) and FN1 (encoding fibronectin) is increased in ccRCC tumor samples compared to adjacent tissue." (PMID 39409411, 2024). "Multivariate cox regression analysis showed that high FN1 protein expression in ESCC tumor tissues was an independent risk factor for low survival in ESCC patients (P < .05)." (PMID 37026938, 2023). "After elucidating the biological function and potential regulatory pathways of FN1, we analyzed the association of FN1 mRNA expression with tumor-infiltrating immune cells." (PMID 36035176, 2022). "Taken together, we demonstrated that the HOXD11/FN1/MMP2/MMP9 axis was an underlying molecular mechanism promoting tumor invasion and metastasis via an EMT-like phenotype in PSCC." (PMID 36151071, 2022). "Through Western blotting, we found that Tspan9 overexpression was associated with marked FN1 upregulation in these OS tumor cells." (PMID 35280793, 2022). "It is worth noting that FN1 was an important oncogene, associated with tumor immune microenvironment." (PMID 35893817, 2022). "FN1, encoding an extracellular matrix protein, exerts its oncogenic role by modulating tumor extracellular matrix remodeling, motility, and metastasis in multiple solid tumors." (PMID 36333284, 2022). "The TIMER, GEPIA, TISIDB, and cBioPortal databases investigated the association of FN1 with tumor immune infiltration and validated using immunohistochemistry." (PMID 36081567, 2022). "It was suggested that activation of the NLRP3 inflammasome complex (associated KGs: FN1) would be an innovative therapeutic pathway to control tumor growth." (PMID 35617355, 2022). "FN1 overexpression was significantly associated with males, advanced clinical stages, advanced tumor classification, and high death rate (all P < 0.05)." (PMID 34688260, 2021). "FN1 was also a core gene of mrDEGs network and its encoded fibronection distributed in BC cell matrix affecting tumor progression." (PMID 33439992, 2021). "The FN1 gene encodes the fibronectin glycoprotein that promotes tumor migration and invasion and suppresses cell apoptosis via the focal adhesion kinase (FAK) pathway." (PMID 34203272, 2021). "The associations between FN1 expression and some clinical parameters, including gender, age, tumor stage, lymph mode metastasis, TNM classification, and smoking status, were investigated." (PMID 34746236, 2021).
tumor (continued). "These all indicated that the expression level of FN1 was closely linked to tumor initiation, development and progression." (PMID 33962392, 2021). "FN1, a gene associated with adhesion and extracellular matrix remodeling, suppresses apoptosis, promotes epithelial cell migration, and drives tumor development in various cancers." (PMID 34688260, 2021). "Even more striking, in tumours that contained FN1‐deficient WM266‐4 cells, 501mel cells outgrew the incompatible WM266‐4 FN‐kd cell population." (PMID 32145051, 2020). "Taken together, the results from our study suggest that OCAMs are present within the tumor microenvironment of peritoneal metastasis in OvCa, and express FN1 causing platinum‐resistance in OvCa cells via the activation of the Akt signaling pathway." (PMID 31904865, 2020). "While a number of studies highlight FN1’s aberrant expression in tumor tissue for diagnostic and therapeutic targeting purposes, our work suggests exciting new mechanisms by which FN1 can promote cancer." (PMID 32630254, 2020). "This idea was further corroborated by findings with WM266‐4 cells in which FN1 was depleted by RNAi; the loss of FN1 profoundly delayed tumour growth." (PMID 32145051, 2020). "This study suggests that high stromal FN1 expression is associated with aggressive tumor characteristics in patients with resected PDAC." (PMID 30736807, 2019). "For case 3, FN1 seemed to be the key molecular hub as well, and it was one of the reasons for clinical decision to rely on tumor mutational burden and PD-1 ligand expression and treat the patient with immune therapies, rather than small molecules." (PMID 32117783, 2019). "Many over-expressed genes in tumor-associated T cells were involved in tissue remodeling (e.g., Col1a1, Col4a1, Fn1, Lamc1, Mmp2, Mmp10, Timp3) and cell motility/adhesion (Rhoc, Itga1, Itgav)." (PMID 31477729, 2019). "Stromal FN1 expression was associated with aggressive tumor properties, including larger tumor size, more advanced T stage and N stage, and worse AJCC stage." (PMID 30736807, 2019). "In the miRNA-mRNA negative regulatory networks, miR-204-5p regulated the largest number of target genes, such as TNFRSF12A. miR-146b, miR-204, miR-7-2, and FN1 were associated with tumor stage in PTC, and TNFRSF12A and CLDN1 were related to prognosis." (PMID 30414611, 2018). "FN1 was also involved in this pathway and the expression level of FN1 was closely associated with tumor growth and metastasis." (PMID 29050278, 2017). "High FN1 expression or up-regulation in tumor cells has been associated with radioresistance, tumor progression and metastatic outgrowth." (PMID 24887580, 2014). "Accordingly, expression of hallmark EMT genes such as Snai1/Snail1 and Fn1 was downregulated in the presence of a JNK inhibitor in conditions that increased expression of the Cdh1 gene in Amela tumor lines." (PMID 23173060, 2012). "Notably, ITGB8 + macrophages exhibited elevated levels of pro-tumorigenic markers associated with M2-like tumor-associated macrophages, including FN1, IL1β, CCL4L2, and CCL3L1." (PMID 39743547, 2025). "In addition to FN1, high risk of tumor recurrence was associated with higher expression of ITGAV, ITGB1 and ITGB6." (PMID 40423510, 2025). "The C3 FN1+ TCs distinguished themselves through their strong association with omental tissue, suggesting their role as metastasis drivers and early facilitators of tumor nesting." (PMID 40612060, 2025). "A picture emerges where the tumour-associated matrix promotes an immune-evasive, pro-metastatic environment, often through modulation of common and abundant matrix components, including collagen I, FN1, and hyaluronic acid (HA)." (PMID 38791926, 2024). "The FN1 (fibronectin) exosomal protein, known to be widely expressed in different tumor cells, may serve as a potential diagnostic marker in NSCLC LC diagnosis based on the proteomic analysis of patients with confirmed LC." (PMID 38558729, 2024).
tumor (continued). "In combination with the analysis results, COL10A1/FAP/FN1 were mainly positively correlated with most of the tumor immune cells, which might be associated with an enhanced tumor immune response." (PMID 38063927, 2023). "Moreover, FN1 showed a significant association with tumor-infiltrating immune cells and immune checkpoint inhibitors." (PMID 36035176, 2022). "FN1 is overexpressed in multiple cancer types and is associated with tumor metastasis." (PMID 36151071, 2022). "Interestingly, no change in expression levels of mesenchymal-associated genes VIM, EGFR, FOSL1 and FN1 was observed between CTCs and their primary tumours in any of the models." (PMID 34206049, 2021). "We discuss the involvement of fibroblasts and in particular of cancer-associated fibroblasts (CAFs) in the FN1 production and assembly and the effects in tumor progression, invasion and metastasis with a focus on the role of extracellular vesicles (EVs) in FN1-driven signaling." (PMID 33731188, 2021). "Moreover, increased FN1 expression in tumor tissue has been linked to a poorer prognosis in cancer patients." (PMID 32630254, 2020). "FN1, derived from tumor-associated fibroblasts, stimulates cancer cell invasion after assembly." (PMID 32337286, 2020). "In pFN-deficient mice, obtained by conditional KO of the Fn1 gene in the liver, von Au and colleagues showed that a decrease in pFN reduces tumor angiogenesis, tumor growth and bone metastasis through an apparent feed forward upregulation of its own production and by modulating the response to VEGF." (PMID 32426283, 2020). "In CRC, a single nucleotide polymorphism in FN1 was found to be associated with tumor shape." (PMID 31850052, 2019). "Additionally, miR-146b, miR-204, miR-7-2, and FN1 were associated with the tumor stage of PTC, and TNFRSF12A and CLDN1 were related to the prognosis of PTC." (PMID 30414611, 2018). "Reports have shown that FN1 is associated with tumor migration and invasion." (PMID 25167886, 2014). "However, the expression of several genes implicated in tumor metastasis including fibronectin (FN1) was upregulated in aggressive cells." (PMID 19116033, 2008). "Furthermore, the overactivation of STAT3 is often associated with inflammatory responses in the tumor microenvironment, and FN1 may also participate in these inflammatory responses during extracellular matrix remodeling." (PMID 40772037, 2025). "Additionally, cytoplasmic FN1 is significantly associated with advanced tumor stage and OS rate." (PMID 34688260, 2021). "Mechanistically, miR-613 has been shown to inhibit tumor cell invasion and migration by directly targeting fibronectin 1 (FN1), a key extracellular matrix component involved in cell adhesion, motility, and metastatic dissemination." (PMID 41596525, 2026). "CONCERT learns perturbation effects as functions of spatial context rather than as slide specific lookups, and therefore transfers across slides: it recovers Fn1 depletion in the tumor core with enrichment at the surface, matching the expected spatial pattern." (PMID 41292874, 2025). "In our data, we observe that the expression of FN1 was significantly higher in α‐SMA+ stroma than in tumor or normal tissues across all three tumor grades." (PMID 39245631, 2025). "Genes that were identified as markers of TAM2 in human ccRCC cells, including Fn1, F13a1 and Gas7 were more highly expressed in Mono-macrophage cluster 2 cells from tumours than from normal kidneys." (PMID 40473819, 2025). "Members of the miR-29 family suppress collagen and fibronectin gene expression (e.g., COL1A1, COL3A1, FN1), thereby limiting excessive desmoplasia characteristic of aggressive tumor stroma." (PMID 41226828, 2025). "In order to provide additional evidence that there was a connection between tumor subtypes that had a higher FN1 expression and the growth and metastasis of the tumor, we decided to investigate the ST." (PMID 40612060, 2025).